C11orf42 (chromosome 11 open reading frame 42)
Synonyms: MGC34805
Tractability: Antibody: the Human Protein Atlas places it where antibodies can reach.
Gene: Protein-coding gene on chromosome 11 (6,205,557 to 6,211,135, forward strand). Ensembl gene ENSG00000180878.
Subcellular location: Cell projection, cilium, flagellum
Subcellular location (Human Protein Atlas): Plasma membrane; Nuclear membrane; Vesicles
Gene Ontology:
Cellular component: sperm flagellum; motile cilium
Genetic constraint (gnomAD): Loss-of-function variants: 24 observed, 27.62 expected, observed/expected ratio (o/e) 0.87, 90% interval 0.63 to 1.22. The upper end of that interval is the gene's LOEUF score, 1.22, which puts it in group 5 of 6, group 1 being the genes least tolerant of losing a copy. Missense variants: 452 observed, 436.27 expected, observed/expected ratio (o/e) 1.04, 90% interval 0.96 to 1.12. Synonymous variants: 186 observed, 190.5 expected, observed/expected ratio (o/e) 0.98, 90% interval 0.87 to 1.1.
Homologues: Orthologues: chimpanzee C11H11orf42 (99% identical), macaque C14H11orf42 (95% identical), dog C11orf42 (90% identical), pig C11orf42 (88% identical), mouse Gm5901 (86% identical), rabbit C11orf42 (81% identical), rat C1h11orf42 (78% identical), guinea pig C11orf42 (73% identical).
Diseases named in the same sentence as C11orf42 in open-access papers:
C11orf42 is named in the same sentence as 8 diseases in open-access papers, as found by Europe PMC text mining. Sharing a sentence is not in itself a finding about the gene and the disease. The quoted sentences say what the papers report.
endometrium adenocarcinoma (1 paper, 2021). An adenocarcinoma arising from the uterine body cavity. "C11orf42 mRNA is moderately expressed in adult testis, upregulated in enriched round spermatids and although it is likely expressed in endometrium adenocarcinoma its RNA profile in control tissues does not mark it out as a bona fide CT gene." (PMID 33426787, 2021).
glioblastoma (1 paper, 2022). The most malignant astrocytic tumor (WHO grade IV). "Moreover, CRISPR screens identified C11orf42 as contributing to fitness and proliferation in lymphoma, glioblastoma and leukaemia cell lines (BioGRID gene ID 160298)." (PMID 35333855, 2022).
liver cancer (1 paper, 2021). An epithelial or non-epithelial malignant neoplasm that arises from the liver. "Given that SNX5 is a negative prognostic marker for liver cancer and plays a role in promoting thyroid cancer progression by stabilizing growth factor receptors, C11orf42 may contribute to these pathological processes via its interaction with SNX5." (PMID 33426787, 2021).
thyroid tumours (1 paper, 2022). "In humans, C11orf42 is expressed in testis and is highly expressed in thyroid tumours." (PMID 35333855, 2022).
C11orf42 also shares sentences with these, for which no sentence is quoted: cancer (1 paper); leukaemia (1); lymphoma (1); thyroid cancer (1).